S100B (S100 calcium binding protein B)
Diseases named in the same sentence as S100B in open-access papers (continued):
Sharing a sentence is not in itself a finding about the gene and the disease.
tumor (187 papers, 1998 to 2026). "Our study showed that the presence of mutated BRAF ctDNA and high levels of the tumor marker S100B in early postoperative blood samples predicted the highest probability of disease recurrence and the worst prognosis." (PMID 39387479, 2024). "Studies demonstrated neurotrophic and neuroprotective effects of S100b, however, increased concentrations are also associated with tumor progress and the progression of neurodegenerative diseases." (PMID 38405120, 2024). "Some members of this family, such as S100A4, S100A8/A9, S100P, and S100B, mediate the interaction between tumor and stromal cells, and thus, have been implicated in tumor progression, angiogenesis, and metastasis." (PMID 38499391, 2024). "Association of overall survival (OS) and disease‐free interval (DFI) with first postoperative plasma levels of S100B tumor marker in combination with BRAF mutation status." (PMID 39387479, 2024). "Association of overall survival (OS) and disease‐free interval (DFI) with preoperative plasma levels of S100B tumor marker in combination with BRAF mutation status." (PMID 39387479, 2024). "We confirmed Cd68/Aif1-expressing tumour-associated microglia and Gfap/S100b-expressing astrocytes in close proximity to proliferating (MKI67-positive) tumour cells within the interface of drug-treated PDOX." (PMID 37127652, 2023). "In the balanced validation cohort-B (increased to n = 86 per the discovery cohort size), there was a significant association between S100B levels and tumor volume in male VS patients (Padj = 0.051 was considered significant for FDR of 0.10)." (PMID 37948527, 2023). "Recently, an association between increased S100B+ folliculo-stellate cells and lower tumor proliferation was positively related to the expression of estrogen receptor-α and FSH in gonadotropinomas." (PMID 37958702, 2023). "In the RLM assessing the relationship of biomarker levels and tumor volume, a significant association was found for S100B, with a significant sex effect among females (all Padj < 0.05)." (PMID 37948527, 2023). "S100B overexpression in gliomas enhances infiltration of tumor-associated macrophages that are mainly immunosuppressive in these tumors." (PMID 36652782, 2023). "The overall percentage of S100B + cells was associated with lower proliferative properties and positively correlated with ERα expression in gonadotroph tumours." (PMID 35139928, 2022). "S100B encodes S100 calcium-binding protein B, a molecule associated with tumour metastasis and progression, which regulates the proliferation and metabolism of cancer cells through physical interactions with other molecules." (PMID 35785160, 2022). "Analysing 20 areas from 5 independent gonadotroph tumours, we found that higher percentages of S100B + cells were associated with lower percentages of Ki67." (PMID 35139928, 2022). "A Ki67 index ≥ 3, a mitosis count > 2/10 per high power fields, and a proliferative status, were all associated with fewer S100B + cells in gonadotroph tumours." (PMID 35139928, 2022). "S100B expression was positively correlated with multiple immune cells tumor infiltration and associated with chemokines/chemokine receptors and immune checkpoint genes." (PMID 35368338, 2022). "Initial diagnostic immunostains of the tumor showed vimentin immunoreactivity and patchy staining for S100β." (PMID 33707600, 2021). "Another significant factor in the univariate analysis was an elevated level of the tumor marker protein S-100B, which was associated with a significantly increased primary resistance, both in the univariate and in the multivariate logistic regression analysis." (PMID 32331243, 2020). "The serum levels of S100B, which was found in all CM ectosome samples in the present study, is linked to the tumor burden and reflects a clinical stage of CM." (PMID 32331267, 2020). "The serum S100B level is linked to the tumor burden and reflects clinical stage and tumor progression as reported by some." (PMID 22287956, 2012).
tumor (continued). "Moreover, the author performed subgroup analysis by SVID (subarachnoid vessel involvement by the tumor), which is the confounding factor in the diagnostic value of S100B." (PMID 40814421, 2025). "We have shown for the first time that the combined determination of the ctDNA BRAFmut oncogene (liquid biopsy) and the high level of tumor marker S100B in pre‐ and postoperative plasma samples can identify patients with the worst prognosis and the highest risk of tumor recurrence." (PMID 39387479, 2024). "S100B is a candidate biomarker whose plasma values were significantly associated with tumor volume." (PMID 37948527, 2023). "We next investigated whether the percentage of intratumoural S100B + cells at the whole tumour level was associated with the clinicopathological characteristics of PitNETs analysed." (PMID 35139928, 2022). "Such spatial associations suggest that S100B + folliculostellate cells could play a role in gonadotroph tumorigenesis, and may contribute to the maintenance of tumour cells in a low proliferating, FSH + /ERα + differentiated state." (PMID 35139928, 2022). "Indeed, in gonadotroph tumours, not only was a Ki67 index ≥ 3% significantly associated with fewer S100B + cells, but also a mitosis count > 2/10 per HPFs, and the proliferative status." (PMID 35139928, 2022). "Previous studies showed that the release of S100B protein, a neurotrophic protein expressed by enteric glia cells in the gut, is commonly upregulated in various models of cancer and is often associated with tumor progression and prognosis." (PMID 31266264, 2019). "Specifically in epithelial regions, S100B was found to be downregulated in secondary microvasculature when compared to primary tumours." (PMID 41549158, 2026). "Head MRI, whole‐body imaging like PET‐CT, CT, or skeletal scintigraphy combined with LDH and tumor marker S100B are used in advanced stages." (PMID 40344340, 2025). "Nonetheless, S100B’s sensitivity for early response detection remains modest, particularly in patients with low tumor burden or isolated organ metastases (e.g., CNS or subcutaneous sites)." (PMID 41374434, 2025). "The principal tumor cluster shared many of the same markers as the parental tumors, such as S100b, Postn, and Mcam." (PMID 40571713, 2025). "Considering dyNF-like tumors, we identified two dyNF types, where tumor cells (TCs) were S100B+/SOX10+ (dyNF S100b+ type) or S100B−/SOX10+ (dyNF S100b− type)." (PMID 41223283, 2025). "This study demonstrates the benefit of determining S100B tumor marker levels in stages I‐III for determining prognosis." (PMID 39387479, 2024). "The combination of primary tumor localization, Clark invasion level, pT category, baseline M stage, and baseline serum S100B level resulted in an excellent AUC value of 0.822 [95% CI 0.727; 0.916], p < 0.001." (PMID 39272837, 2024). "Several studies have demonstrated the prognostic significance of the S100B tumor biomarker in generalized melanoma." (PMID 39387479, 2024). "To understand differences between ICB regimens with respect to tumor intrinsic properties, we selected tumor cell regions using S100B/PMEL antibodies for digital spatial profiling." (PMID 38594286, 2024). "The preoperative plasma samples for the analysis of S100B tumor marker were available in 46 patients (57.5%)." (PMID 39387479, 2024). "The combination of primary tumor localization, Clark invasion level, pT category, baseline M stage, and baseline serum S100B level was excellent at distinguishing patients who were likely to be progression-free beyond 18 months from those who were not." (PMID 39272837, 2024).
tumor (continued). "Considering that MCP-3 and S100B are the only biomarkers significantly associated with patients’ preoperative hearing and tumor size, 128 panels containing both MCP-3 and S100B were analyzed." (PMID 37948527, 2023). "Serum levels of S100B increase with tumor growth and are used to monitor patients in advanced stages of the disease." (PMID 36831440, 2023). "Enrichment of S100B has been shown to be sufficient to drive angiogenesis, increase tumor inflammation, enhance growth, and drive migration, all of which are features of GBM." (PMID 37377888, 2023). "Tumor markers in the blood, including S100B, CEA, CA-19–9, CA125, CA15-3, CA72-4, cyfra, synaptophysin, and chromogranin A, were not elevated." (PMID 35501497, 2023). "While Il4r and Igf1 mRNA was expressed in Cd68/Aif1-positive tumour-associated microglia throughout drug-treated PDOX, Il4 expression co-localised with Gfap/S100b-expressing astrocytes exclusive to the interface region of drug-treated PDOX." (PMID 37127652, 2023). "Patients with tumor infiltration into deeper tissue layers had higher S100B concentrations, with the highest values detected in stage IV." (PMID 38202181, 2023). "Whilst the 9L tumor is not considered an invasive model, it shares some histological similarities with GBM tumor cells such as S100B positive." (PMID 36269130, 2023). "We found that S100B was observed in the immune cell at the tumor tissues, especially NK cell in HCC." (PMID 35368338, 2022). "Of note, in gonadotroph tumours, it would have been interesting to also compare S100B + cells to SSTR3 + cells." (PMID 35139928, 2022). "Quantification of S100B + cells at the whole tumour level highlighted that tumour tissue showed a significant decrease in S100B + cells (median 0.18%) compared to normal APG (median 3.95%)." (PMID 35139928, 2022). "Here, we assessed the presence and distribution of S100B + cells within the TME of PitNETs in order to provide a refined cartography of S100B + cells within tumours and between patients." (PMID 35139928, 2022). "In order to investigate the intratumoural distribution of S100B + cells in our cohort of 26 gonadotroph tumours, we defined for each sample multiple tumour areas on the same tumour slide." (PMID 35139928, 2022). "We uncover an interpatient and an intratumoural heterogenous distribution of S100B + cells in gonadotroph tumours." (PMID 35139928, 2022). "It is unclear if these tumours, referred to as primitive GCTs, are derived from mesenchyme of an NCC origin that differs from traditional GCTs or if these tumours have lost S100B expression." (PMID 35323240, 2022). "This quantification confirmed that the percentage of S100B + cells was lower in the tumour tissue compared to adjacent APG tissue, independently of the PitNET subtype." (PMID 35139928, 2022). "High-throughput histological analysis of S100B-stained tumour sections of 54 PitNETs revealed a significant decrease in S100B + cells in PitNETs compared to the normal anterior pituitary." (PMID 35139928, 2022). "At physiological levels, S100B regulates cancer cell proliferation and metabolism to modulate malignant tumor processes." (PMID 35368338, 2022). "The presence of an intratumoural heterogeneity and the existence of low- and high-expressing S100B areas was intriguing and made us question the functional consequences of such a spatial cell distribution in gonadotroph tumours." (PMID 35139928, 2022).
tumor (continued). "Our work highlights a potential role for intratumoural S100B + cells in modulating the proliferation, the differentiation, and the hormonal production of gonadotroph tumour cells." (PMID 35139928, 2022). "More in-depth studies are needed to reveal the role of S100B in the tumor microenvironment to be its more convincing in HCC." (PMID 35368338, 2022). "Spatial analysis of cell distribution in different tumour areas of 26 gonadotroph PitNETs further revealed an intratumoural heterogeneity of S100B + cells." (PMID 35139928, 2022). "Our work paves the way towards a refined view of gonadotroph tumour heterogeneity and towards a better understanding of the role of S100B + folliculostellate cells in gonadotroph tumours." (PMID 35139928, 2022). "In these 5 tumours, the percentage of ERα-expressing and LH-expressing cells seemed to show less intratumoural heterogeneity than S100B-expressing, FSH-expressing, Ki67-expressing, and SSTR2-expressing cells." (PMID 35139928, 2022). "Other intracellular markers, S100β and Nestin were expressed at similar intensity but in a lower proportion of tumours (70% and 60%, respectively)." (PMID 34885099, 2021). "Like the parent tumor, 2XSB cells were immunoreactive for Sox10 (80–100% positivity), nestin (90–100% positivity) and S100β (80–100% positivity)." (PMID 33707600, 2021). "An exception was S100β where only a proportion of tumour cells exhibited strong expression, with positively stained cells often clustered in small areas." (PMID 34885099, 2021). "In parallel, a significant increase of S100B protein release was observed in peritumoral (+400%; P < .01), UC (733%; P < .001) and tumour culture medium (1108%; P < .001) vs control group, respectively." (PMID 32022398, 2020). "For S100B tumor marker the population estimate and BSV of MTT were also fixed to the values obtained in the model for LDH concentrations." (PMID 32366871, 2020). "S100B is expressed in melanocyte-derived tumours and mature astrocytes, where it plays an important role in neurite extension." (PMID 34094300, 2020). "The RAGE (receptor for advanced glycation end-products) and its ligands, high mobility group box 1 (HMGB) and S100B have documented roles in skeletal muscle and in tumor." (PMID 33291708, 2020). "This tumor progression was in turn linked to the time course of LDH, MIA and S100B serum concentration dynamics that were produced by a first-order rate constant and cleared at a first-order elimination rate in healthy subjects." (PMID 32366871, 2020). "S100A1, S100A4 and S100B protein expression are related to the increasing levels of tumor malignancy." (PMID 31968004, 2020).
tumor (continued). "In multivariate Cox regression analysis of stage IV patients S100A8/A9, LDH, and S100B were independent prognostic factors with S100B as most powerful marker highlighting the extraordinary impact of tumor burden in stage IV disease." (PMID 31806053, 2019). "Other serum tumour markers are S-100B, melanoma inhibitor activity protein (MIA) Enolase, tumour associated antigen 90 immune complex and more recently YKL-40)." (PMID 29492238, 2018). "Elevated S100β serum levels at week 7 post-implantation coincided with increased tumor burden and manifestation of distant micrometastasis (two-sided Student’s t test, p = 0.0012)." (PMID 28399921, 2017). "Of note, reduced tumor aggression was marked by a decrease in S100β protein in both in vivo endocrine resistant models and in ex vivo tumors from patients with endocrine resistant breast cancer." (PMID 28399921, 2017). "Surgical resection of the patient primary tumor returned elevated levels of serum S100β to normal (6 individual patients with elevated S100β, p = 0.023)." (PMID 28399921, 2017). "The S100β protein is often used as a tumor marker, and it is believed to exhibit diverse biological functions." (PMID 27695124, 2016). "In this setting, trametinib suppressed both subcutaneous growth and plasma S100B levels and extended the time for the mice to achieve a tumor size that required ethical sacrifice." (PMID 25228592, 2014). "Immunohistochemistry shows patchy expression of GFAP and S100b protein in tumour cells, a feature seen in a some MG patients." (PMID 23762429, 2013). "Whilst RAGE signalling is induced by a wide range of ligands, we only tested S100B which is the most extensively characterized RAGE ligand in functional tumor cell studies." (PMID 24260107, 2013). "Another possibility would be that primary tumours have different expression patterns of protein S100B." (PMID 21810220, 2011). "Since the analysis of serum S100B showed the highest sensitivity and specificity of all tumour markers examined in CM and it is fairly inexpensive, numerous clinicians include its measurement in routine follow up of CM patients." (PMID 21810220, 2011). "Patients with elevated MIA-, S100B- or LDH-levels had a 6.5-fold, 4.2-fold or 6.1-fold higher mortality risk compared to patients with normal tumor markers." (PMID 21935432, 2011). "Revealing such associations would potentially promote the use of preoperative S100β level as a marker of tumour effect on brain tissue and postoperative S100β level as a marker for early detection of ongoing postcraniotomy brain damage." (PMID 17020600, 2006). "Our study indicates that the measurement of S-100B as a tumour marker in the management of patients with cutaneous malignant melanoma has clinical significance." (PMID 9649135, 1998). "Most of the cell lines are highly enriched for S100B staining, suggesting that very few other cells/cell types are present; those bearing a somatic NF1 mutation in the majority of cells are enriched for the two-hit tumor Schwann cells." (PMID 41564118, 2026). "Furthermore, S100B levels reflect tumor mass, with serum levels of this marker predicting treatment effectiveness." (PMID 40535809, 2025).